INS (insulin)
Diseases named in the same sentence as INS in open-access papers (continued):
Sharing a sentence is not in itself a finding about the gene and the disease.
Hyperinsulinemia (continued). "Decreased carcinoembryonic antigen related cell adhesion molecule 1 leads to a decrease in insulin clearance, exacerbating hyperinsulinemia." (PMID 30406180, 2018). "First, IR overexpression sensitizes cancer cells to the pleiotropic effects of insulin, in particular in all clinical conditions with hyperinsulinemia." (PMID 30453495, 2018). "Defects in insulin action at first can be compensated by increased insulin secretion, resulting in hyperinsulinemia, so as to maintain blood glucose homeostasis." (PMID 29515798, 2018). "With hepatic lipid reduction, DZF indirectly activates hepatic insulin signaling pathway, improves hyperinsulinemia, and promotes glycogen synthesis." (PMID 29593575, 2018). "Over time, with persistent nutrient overload, cardiomyocytes become desensitized to systemic hyperinsulinemia insulin-signaling pathways resulting in impaired Akt signaling via various mechanisms such as exacerbation of lipotoxicity." (PMID 30089498, 2018). "Decreased IRS1 in the liver can cause the fasting hyperinsulinemia often observed in patients with NAFLD, since higher serum insulin levels are needed to suppress gluconeogenesis in the liver." (PMID 29749571, 2018). "The ability to reduce insulin secretion, and therefore hyperinsulinemia, through eGLP-1R antagonism is a promising and novel approach to managing equine insulin dysregulation." (PMID 29404215, 2018). "Leptin was 23.95 ± 17.51 ng/mL in those with insulin below the normal range, 31.15 ± 17.20 ng/mL in those whose insulin was within the normal range, and 63.88 ± 7.40 ng/mL in those with hyperinsulinemia." (PMID 29890036, 2018). "Insulin infusion (to produce hyperinsulinemia) has been shown to have conflicting effects on blood pressure (BP) depending on strain and species studied." (PMID 30249002, 2018). "Hyperinsulinemia further drives hepatic lipogenesis, particular when liver is still sensitive to insulin and/or the Snail1 arm is dysfunctional, thereby exacerbating NAFLD." (PMID 30013137, 2018). "Examination of deposited microarray data from a study focusing on hyperinsulinemia indicated that RARRES1 was also markedly decreased after insulin treatment in human skeletal muscles." (PMID 30557378, 2018). "study did show hyperinsulinemia (via increased insulin AUC), which likely contributed to the lower glucose levels during the GTT." (PMID 29981201, 2018). "This is further compounded by increasedde novo lipogenesis, which is driven by hyperinsulinemia and retained sensitivity to the lipogenic effects of insulin in an otherwise insulin-resistant state." (PMID 29946426, 2018). "All together, these results strongly suggest that down-regulation of PRKD2 expression is sufficient to increase insulin level, and support a hyperinsulinemia-primary model that IR and obese progressively developed following hyperinsulinemia." (PMID 29789568, 2018). "Sodium-glucose cotransport 2 (SGLT-2) inhibitors are a class of human anti-diabetic drugs that offer a novel therapeutic option for treating insulin dysregulation and hyperinsulinemia in horses through targeting renal glucose reabsorption." (PMID 30212530, 2018). "Exposure to high levels of fatty acids can reduce the sensitivity of cells to insulin and induce hyperinsulinemia, which in turn increases apelin secretion from the adipose tissue." (PMID 30140406, 2018). "An increase in protein load for insulin synthesis in β-cells due to hyperglycemic conditions can result in β-cell expansion and generate hyperinsulinemia as a compensatory mechanism." (PMID 29565831, 2018). "There occurs hyperinsulinemia, enhanced hepatic gluconeogenesis, and glucose output in an insulin resistant status." (PMID 29976917, 2018). "Hyperinsulinemia can disturb the physiological function of several vital organs via the impairment of insulin signaling and the disturbance of intracellular signaling transduction." (PMID 30233495, 2018).
Hyperinsulinemia (continued). "Dairy products have been identified as potent insulin secretagogues, as their consumption stimulates acute hyperinsulinemia." (PMID 30364240, 2018). "This hyperinsulinemia is an indirect effect of GC on islet insulin hypersecretion, as demonstrated in male and female rats treated with dexamethasone." (PMID 30018561, 2018). "Rodent models treated with insulin and/or human chorionic gonadotropin (hCG) offer the potential to study the cellular and molecular processes in response to hyperinsulinemia, and hyperandrogenism alone or in combination." (PMID 29719598, 2018). "Having higher GAA concentrations appears to be accompanied by elevated levels of insulin circulating in the blood, suggesting a possible link between excess GAA and hyperinsulinemia, a well-known cardiometabolic risk factor." (PMID 29342866, 2018). "In another study, ZDF rats displayed a significantly higher RQ than their lean littermates during hyperinsulinemia and, as the insulin levels declined, the RQ gradually decreased below the value of the lean animals." (PMID 30687238, 2018). "Insulin dysregulation (ID) with basal or postprandial hyperinsulinemia is one of the key findings in horses and ponies suffering from the equine metabolic syndrome (EMS)." (PMID 29351765, 2018). "Hepatic extraction of insulin and the body’s metabolism of insulin is reduced with increasing iron storage, leading to peripheral hyperinsulinemia." (PMID 29342898, 2018). "In the pancreas, FOXO1 promotes beta-cell differentiation and insulin secretion, probably contributing to hyperinsulinemia in T2D." (PMID 30602666, 2018). "Consistent with a role for CEACAM1 in insulin clearance, obese rats display reduced insulin clearance (as measured by steady-state C-peptide/insulin molar ratio) and hyperinsulinemia." (PMID 28396653, 2017). "Under these circumstances, excessive insulin is secreted by body to maintain the stability of blood glucose, leading to hyperinsulinemia; thus, it is important to repair the insulin signaling pathway of peripheral tissue in the treatment of T2DM." (PMID 29187178, 2017). "In the only case that this did not occur, was under the pro-Tr1 environment, where a regulatory phenotype is attained independently of the insulin level, avoiding a pro-inflammatory condition even under the presence of hyperinsulinemia." (PMID 28651594, 2017). "Activation of hepatocyte CB1 inhibits the insulin clearance by insulin degrading enzymes, thus contributing to hyperinsulinemia and increased glycogenosis." (PMID 28837063, 2017). "Other analyses confirm that reductions in caveolin-3 inhibit insulin-stimulated glucose uptake in cardiac myoblasts and myocytes, and that hyperinsulinemia in cardiac myoblasts reduces caveolar levels of caveolin-3 and insulin-dependent phospho-Akt." (PMID 29202762, 2017). "The resistance of the body toward insulin results in increased production of insulin in the pancreas leading to hyperinsulinemia." (PMID 28620607, 2017). "They showed that acute phase insulin secretion was diminished and hyperinsulinemia during the late phase was present, despite normal insulin sensitivity." (PMID 28705209, 2017). "Compared with adipose tissue in other body parts, visceral adipose tissue is more resistant to insulin, and hyperinsulinemia promotes the liver lipogenesis and raises the serum ALT levels." (PMID 28399807, 2017). "Insulin levels, in serum of 5h-fasted animals, revealed that the hfd-induced compensatory hyperinsulinemia in WT mice, was significantly prevented in Tg, supporting the notion that KAP protects from hfd-induced IR." (PMID 29170528, 2017). "It has been proposed that this hyperinsulinemia is the result of both increased insulin production and decreased insulin clearance." (PMID 28134848, 2017).
Hyperinsulinemia (continued). "First, our result revealed that aging is associated with elevated plasma insulin and triglyceride along with a sustained Akt phosphorylation, suggesting hyperinsulinemia, chronic activation of Akt, onset, and development of insulin insensitivity in aging." (PMID 28681509, 2017). "The two nodes whose transitions in response to transient perturbations varied more among environments (i.e., basal insulin versus hyperinsulinemia) were IL10 and, trivially, INSULIN itself." (PMID 28651594, 2017). "Consistent with the role for insulin to up-regulate eNOS transcription, it is demonstrated that mice with hyperinsulinemia have increased eNOS mRNA and NO production." (PMID 29213078, 2017). "To simulate the effect of hyperinsulinemia we extended the previous network to add the regulation of IL-10 by insulin via the AKT pathway; and the STAT3-signaling cytokines: IL-10, IL-6, and IL-21 all use STAT3." (PMID 28651594, 2017). "Normoglycemia in these rats was supported by hyperinsulinemia, provided by insulin hypersecretion from the pancreatic β-cells." (PMID 28380195, 2017). "Previous studies indicate the correlation between plasma glucose metabolism and intracellular antioxidant enzymes, and overexpression of antioxidant selenoproteins results in hyperinsulinemia with decreased insulin sensitivity." (PMID 28763492, 2017). "Restoration of Pomc expression only in cells with 5-HT2CRs corrects hyperinsulinemia and insulin sensitivity." (PMID 29031711, 2017). "When the loss of hepatic CEACAM1 reaches more than 50% and impairment of insulin clearance develops, chronic hyperinsulinemia followed by hepatic steatosis ensues." (PMID 28396653, 2017). "This creates a need to examine the insulin-deprivation counterpart to our hyperinsulinemia model system, with the latter a question that would need to addressed in vivo and/or with insulin receptor-deficient mast cells in vitro or in vivo." (PMID 29430572, 2017). "Excessive accumulation of lipids in the liver impairs hepatic responsiveness to insulin, leading to elevated levels of glucose and insulin in the circulation, eventually chronic hyperinsulinemia." (PMID 28848738, 2017). "B.Another 3 of the 13 subjects showed evidence of hyperinsulinemia, but missed the fasting insulin cutoff of 12.2 μIU/mL; two of the three also missed the McAuley Index cutoff < 6.07." (PMID 29258604, 2017). "A prolonged QTc interval has been shown to be related to various markers of reduced insulin sensitivity, such as abdominal adiposity, hyperlipidaemia, hypertension and hyperinsulinemia." (PMID 28912840, 2017). "Many factors will promote proteolysis and reduce protein synthesis such as hyposecretion and insufficient supplement of hemopoietin, insulin resistance, insensitivity to growth hormones and insulin-like growth factor, hyperinsulinemia and hyperparathyroidism." (PMID 28540266, 2017). "The obese dams developed hyperinsulinemia, hyperleptinemia and hyperlipidemia as expected, however, insulin emerged as the only factor studied that correlated significantly with offspring hyperinsulinemia." (PMID 28291256, 2017). "In contrast, maternal HFD produced hyperinsulinemia in KO, which expressed four times the plasma insulin as KO from Con-fed dams (P < 0.01), suggesting that ERE-independent signaling is protective against the effects of maternal HFD on insulin production." (PMID 28743985, 2017). "There is a significant correlation at the baseline between CRP and insulin response, and high levels of CRP are associated with hyperinsulinemia." (PMID 28404960, 2017). "Increased level of circulating glucose increases pancreatic insulin secretion resulting in hyperinsulinemia." (PMID 28798859, 2017). "A previous study investigating the role of αCGRP in DIO found αCGRP-deficient mice to exhibit a lower body weight, improved glucose handling and insulin sensitivity which was accompanied by reduced hyperinsulinemia and adiposity compared to controls." (PMID 28666011, 2017).
Hyperinsulinemia (continued). "Complement gene upregulation in AT and adipocytes correlated positively with adiposity and hyperinsulinemia and negatively with the expression of insulin signaling-related genes." (PMID 28559893, 2017). "This combination synergizes their metabolic outcomes, a procedure that renders rat mild hyperglycaemic, obese, insulin resistant, hypercholesterolemic, and hypertriglyceridemic with compensatory hyperinsulinemia." (PMID 28129400, 2017). "It was reported that insulin sensitivity decreases about 30% during puberty, resulting in hyperinsulinemia." (PMID 28330444, 2017). "To determine the effects of MnP on hyperinsulinemia, we measured insulin in the sera of mice treated with MnP while on a HFD." (PMID 29104232, 2017). "IR is directly related to β-cell function and its decreased insulin secretory response and inability to overcome the state of chronic hyperinsulinemia." (PMID 28811774, 2017). "The hyperinsulinemia which is observed in PCOs is mostly a result of increased secretion of basal insulin along with decreased hepatic insulin clearance." (PMID 28915843, 2017). "Together, this demonstrates that altered CEACAM1-dependent insulin clearance pathways drive hyperinsulinemia-mediated link of hepatic steatosis to visceral obesity and increased total fat mass." (PMID 28184213, 2017). "Under high levels of insulin, that simulates an acute hyperinsulinemia condition, the CD4+ T plasticity patterns are altered." (PMID 28651594, 2017). "Hyperinsulinemia due to the insulin resistance affects the Na+-K+ pump activity, it regulates the release of neurotransmitters in presynaptic nerve terminals, and changes gallbladder smooth muscle tone." (PMID 29088261, 2017). "This suggests that maternal hyperinsulinemia is a key programming factor that mediates the effects of maternal over-nutrition on offspring insulin sensitivity." (PMID 28291256, 2017). "Reduced serum insulin levels were also observed with MnP treatment, indicating improved insulin signaling and diminished hyperinsulinemia." (PMID 29104232, 2017). "Drugs that close KATP channels to stimulate the release of insulin are widely used to treat type II diabetes, while drugs that open these channels are used to treat mild forms of hyperinsulinism." (PMID 28276322, 2017). "After establishing the utility of our method across different diseases, we expanded the analysis on a specific disease module, focusing on hyperinsulinism, a medical state in which the levels of insulin in the blood are above the norm." (PMID 28549478, 2017). "It is characterized by increased secretion of insulin from pancreatic β-cells and compensatory hyperinsulinemia." (PMID 27725832, 2016). "GCs also stimulate insulin secretion, and along with the resultant hyperinsulinemia, this interaction of GCs with hyperinsulinemia, modulates food choice to favour sucrose and lard in rodents." (PMID 27929385, 2016). "Insulin-resistant tissues require increased insulin secretion to produce physiological responses, and this compensatory hyperinsulinemia is deleterious both for the overextended β-cell and for its mitogenic effects on cancer cells." (PMID 27577745, 2016). "Of particular interest to our group has been the role of insulin metabolism and hyperinsulinemia in prostate cancer progression." (PMID 27599544, 2016). "Given evidence showing prostate cancer responsiveness to insulin in mouse models and insulin receptor expression by human prostate cancer cells, it is possible that hyperinsulinemia facilitates progression to castration-resistant prostate cancer (CRPC)." (PMID 27599544, 2016). "Hyperinsulinemia due to insulin pellets would be also another potential factor that affects keratinocyte homeostasis." (PMID 27846299, 2016). "On the other hand, IGFBP-1 and IGFBP-2 have a well-known role in metabolic regulation, maintaining blood glucose levels, insulin sensitivity, glucose intolerance, and hyperinsulinemia." (PMID 26858687, 2016).
Hyperinsulinemia (continued). "Diet restriction alleviated all metabolic symptoms except hyperinsulinemia, suggesting the functional role of GPx1 lies in regulating insulin production." (PMID 26861388, 2016). "The lipotoxicity effect of liver impairs the insulin action resulting hyperinsulinemia and subsequent leads to the condition of oxidative stress following chronic inflammation and fibrosis." (PMID 27169860, 2016). "Here, we focused on the characterization of effects in the brain due to hyperinsulinemia and compared regular insulin and insulin detemir in equimolar and equipotent concentrations." (PMID 27589235, 2016). "In these conditions, deterioration of glucose tolerance can only be prevented if beta cells increase their insulin secretory response and maintain a state of chronic hyperinsulinemia." (PMID 26770991, 2016). "SA administration suppressed body weight gain; improved insulin sensitivity, hyperinsulinemia, and hyperleptinemia; attenuated inflammation in the liver and white adipose tissue; and inhibited hepatic lipogenesis and progression of NASH." (PMID 26871288, 2016). "In T2D patients with hyperinsulinemia, metformin improves glycemic control by enhancing insulin sensitivity in muscle increasing glucose uptake and in liver, decreasing the production of hepatic glucose." (PMID 27579154, 2016). "Hyperinsulinemia and low insulin sensitivity were both present in recent-onset and, even more prevalent, in long-standing DM." (PMID 27814399, 2016). "After an initial phase of hyperinsulinemia, the animals developed T2D and lost the capacity to produce sufficient insulin." (PMID 27153060, 2016). "Fasting glucose concentrations were normal in both brothers, with mild hyperinsulinemia in Subject II.4 (17.1 μU/ml) and a normal insulin level of 7 μU/ml in Subject II." (PMID 26902202, 2016). "This is characterized by initial hyperinsulinemia at eight weeks of age followed by decreased insulin levels." (PMID 27595114, 2016). "The pancreatic β-cells react by secreting more insulin, leading to increased circulating insulin concentrations (hyperinsulinemia) to maintain normal plasma glucose concentrations." (PMID 27029038, 2016). "The more insulin resistant a person is, the more insulin is required to keep blood glucose within normal limits rendering the normalization of hyperinsulinemia/IR an important therapeutic target." (PMID 27539049, 2016). "Insulin is another factor that regulates the mTORC1 pathway in skeletal muscle and old people have been shown to be less responsive to hyperinsulinemia than young people." (PMID 26784225, 2016). "Pooled regression analysis indicated that reductions in hyperinsulinemia, gauged as the insulin response during OGTT, leptin and PRA, and enhancement of BRS were independently associated with sympathoinhibition within the cohort." (PMID 27857694, 2016). "These mice developed a marked hyperinsulinemia, resulting from the compensatory insulin secretion from pancreatic beta cells." (PMID 27562101, 2016). "Cholesterol accumulation in pancreatic islets and the resultant hyperinsulinemia led us to evaluate the mechanism by which cholesterol enrichment in pancreatic beta cells modulate insulin exocytosis." (PMID 27282931, 2016). "Insulin resistance leads to increased blood insulin levels, termed hyperinsulinemia, which has been confirmed by several clinical studies to be a predictor of cardiovascular disease." (PMID 27832775, 2016). "Hyperinsulinemia has been known to increase sympathetic output through the sympathoexcitatory effects of increased insulin." (PMID 28066329, 2016). "Insulin resistant IRS-1−/− mice demonstrated insulin secretory defects, hyperplastic islets, hyperinsulinemia, and normoglycemia." (PMID 26937254, 2016). "Overexpression of GPx1 in mice yielded surprising results, leading to reduced glucose clearance, hyperinsulinemia, hyperglycemia, and diminished insulin signaling." (PMID 26861388, 2016).